LIF (LIF interleukin 6 family cytokine)
Description:
Functions as a cytokine that binds to the LIF receptor complex. The LIF receptor complex indeed consists of two signaling receptor subunits IL6ST/gp130 and LIFR that transduce the signal into the cell. Functionally, regulates cell self-renewal, differentiation and survival of embryonic stem cells (ESCs) and is crucial for embryonic implantation (By similarity). Mechanistically, ligand binding to LIFR, induces heterodimerization with IL6ST/gp130 activating JAK tyrosine kinases (JAK1 or JAK2 and to a lesser extent TYK2) bound to their intracellular domains. These kinases subsequently phosphorylate IL6ST/gp130 and LIFR. The tyrosine phosphorylated signaling receptors serve in turn as docking sites for recruitment and activation of signal transducers and activators of transcription (STAT3 and to lesser extent STAT1). In parallel to the activation of the STAT3-pathway, the binding of LIF to the LIF receptor complex leads to the activation of the mitogen-activated protein kinase (MAPK) and the phosphatidylinositol 3-kinase (PI(3)K) pathways. Tyrosine phosphorylation of the p85 subunit of PI(3)K by JAK1 leads to activation of the serine/ threonine kinase AKT (protein kinase B). PI(3)K-dependent signaling is required for efficient self-renewal of murine ES cells, and regulation of ERK activity is functionally important in this response (By similarity). Moreover, induces tyrosine phosphorylation of PTPN11, that associates with IL6ST/gp130-LIFR, which in turn recruits the p85 regulatory subunit of PI(3)K protein kinase, promoting PI3K-AKT activation, and GRB2-RAS-MAPK signaling.
Synonyms: MLPLI; HILDA; CDF; DIA
Tractability: Small molecule: it has a binding pocket of medium quality. Antibody: its Gene Ontology location is reachable by antibodies, with high confidence; UniProt places it where antibodies can reach, with medium confidence; UniProt predicts a signal peptide or a membrane-spanning region.
Gene: Protein-coding gene on chromosome 22 (30,240,453 to 30,246,759, reverse strand). Ensembl gene ENSG00000128342.
Subcellular location: Secreted
Subcellular location (Human Protein Atlas): Cytosol; Predicted to be secreted
Pathways (Reactome):
Immune System: IL-6-type cytokine receptor ligand interactions; Interleukin-10 signaling; Interleukin-4 and Interleukin-13 signaling
Gene Ontology:
Molecular function: cytokine activity; growth factor activity; leukemia inhibitory factor receptor binding; protein binding; signaling receptor binding
Biological process: cell surface receptor signaling pathway via STAT; leukemia inhibitory factor signaling pathway; negative regulation of hormone secretion; positive regulation of cell adhesion mediated by integrin; positive regulation of cell population proliferation; positive regulation of macrophage differentiation; positive regulation of MAPK cascade; positive regulation of mesenchymal to epithelial transition involved in metanephros morphogenesis; positive regulation of peptidyl-serine phosphorylation; positive regulation of peptidyl-tyrosine phosphorylation; positive regulation of receptor signaling pathway via STAT; positive regulation of transcription by RNA polymerase II; regulation of metanephric nephron tubule epithelial cell differentiation; macrophage differentiation; regulation of cell differentiation; cell differentiation; immune response; positive regulation of multicellular organismal process; regulation of cell communication; regulation of multicellular organismal development; regulation of signaling; stem cell division
Cellular component: cytosol; extracellular region
Genetic constraint (gnomAD): Loss-of-function variants: 9 observed, 14.62 expected, observed/expected ratio (o/e) 0.62, 90% interval 0.37 to 1.07. The upper end of that interval is the gene's LOEUF score, 1.07, which puts it in group 4 of 6, group 1 being the genes least tolerant of losing a copy. Missense variants: 240 observed, 277.76 expected, observed/expected ratio (o/e) 0.86, 90% interval 0.78 to 0.96. Synonymous variants: 122 observed, 126.07 expected, observed/expected ratio (o/e) 0.97, 90% interval 0.83 to 1.12.
Homologues: Orthologues: chimpanzee LIF (100% identical), macaque LIF (97% identical), dog LIF (92% identical), rabbit LIF (89% identical), pig LIF (88% identical), guinea pig LIF (85% identical), mouse Lif (80% identical), rat Lif (80% identical), tropical clawed frog LIF (34% identical).
Diseases named in the same sentence as LIF in open-access papers:
LIF is named in the same sentence as 279 diseases in open-access papers, as found by Europe PMC text mining. Sharing a sentence is not in itself a finding about the gene and the disease. The quoted sentences say what the papers report.
Infertility (78 papers, 2006 to 2025). "Mutations in LIF have been reported in infertile women, and these reports concur with the failure of blastocyst implantation in LIF knockout dams and with the observation of high LIF expression in the endometrial glands." (PMID 38443597, 2024). "Abnormalities in LIF expression, particularly abnormal low levels, are associated with embryonic implantation dysfunction, potentially leading to infertility in women." (PMID 39120268, 2024). "In this context, Leukemia Inhibitory Factor (LIF) has been implicated as a contributor to endometriosis associated infertility." (PMID 37033980, 2023). "In the clinic, this immune molecule is considered a possible cause of unexplained infertility, because lower LIF levels have been associated with a higher risk of multiple implantation failures." (PMID 37266451, 2023). "Ultimately, further investigation into the role of LIF across endometriosis subtypes and stages is required to better address its role within both endometriosis-associated infertility and pathophysiology." (PMID 37033980, 2023). "To date, LIF has only been studied within the context of endometriosis-associated infertility however its potential contributions to disease pathophysiology remains to be understood." (PMID 37033980, 2023). "LIF levels in uterine flushings are able to predict likelihood of a successful reproductive outcome in women with infertility of various causes with high sensitivity and specificity at a cutoff point of 2.31 pg/mL." (PMID 35204717, 2022). "In studies conducted about unexplained infertility and recurrent implantation failures, a decrease in LIF expression or mutation of the LIF gene was detected in the treatment groups." (PMID 36246072, 2022). "Although the reason behind this unexpected result remains to be investigated, it is possible that a balanced LIF/LIFR signal is critical for successful pregnancies; both too little and too much LIF production can cause infertility." (PMID 36329823, 2022). "Our study together with other studies confirms that LIF is significantly decreased in endometria from women with infertility-causing conditions, such as RIF30,31." (PMID 30109142, 2018). "Both FOXA2-deficient mouse models are infertile due to defects in embryo attachment and lack LIF expression on GD 410,16." (PMID 29934619, 2018). "In infertile women LIF gene mutations which are statistically significantly (P<0.05) connected to women with infertility and more frequent than in healthy women." (PMID 28845418, 2017). "The prevalence of LIF gene mutations was investigated in a population of infertile women and found a significantly higher frequency of the functionally relevant mutation." (PMID 28845418, 2017). "The vital role of LIF during embryo implantation has been established based on abnormal LIF levels in infertile patients and LIF gene mutations in patients with repeated implantation failure." (PMID 26800213, 2016). "Uterine leukemia inhibitory factor (LIF) is obligatory for blastocyst implantation in mice and associated with infertility in women." (PMID 21611124, 2011). "The expression pattern of this cytokine during the menstrual cycle, and previous clinical associations between LIF deficiency and infertility, suggest LIF has a possible role in the implantation phenomenon." (PMID 19374770, 2009). "In contrast to the present study IL-11, IL-11Rα and LIF staining were decreased in glandular epithelial cells in women with endometriosis associated infertility." (PMID 18047677, 2007). "Infertility has been associated with aberrant expression of immune modulators, including leukemia inhibitory factor (LIF), soluble gp130, and IL-11." (PMID 17118171, 2006).
Infertility (continued). "It has also been stated that acupuncture may be a new tool for infertile women with LIF deficiency, as acupuncture promotes LIF expression to improve implantation." (PMID 40809179, 2025). "Mutations in the LIF gene can result in infertility among mice." (PMID 40733669, 2025). "Heterozygous mutation of the LIF gene results in reduced LIF activity and may be the infertility cause in some women." (PMID 36704201, 2022). "Low levels of LIF are associated with deficient implantation and infertility in humans." (PMID 36090037, 2022). "The level of LIF is closely associated with the degree of bacterial ascension in the upper genital tract and the formation of hydrosalpinx, a common tissue pathology associated with Ct infection in both humans and mice that can cause infertility." (PMID 36329823, 2022). "The authors concluded that the dysregulation of endometrial LIF secretion throughout the menstrual cycle may be a possible cause of unexplained infertility and recurrent implantation failure." (PMID 35216313, 2022). "A study has suggested that abnormal LIF levels may be associated with infertility and low concentration of LIF levels may be associated with unexplained infertility." (PMID 33489035, 2020). "In addition, the frequency of relevant mutations of LIF was enhanced in infertility women, and LIF endometrial expression was impaired in UI women." (PMID 29085337, 2017). "Collectively, loss of LIF signalling has been established in patients with variable pathologies, such as preeclampsia, unexplained infertility, endometriosis, and recurrent implantation failure, indicating its importance for the maintenance of reproductive functions." (PMID 27239344, 2016). "LIF is regarded as an important factor in both murine and human embryo implantation; it is a key regulator of decidualization and LIF-deficient female mice are infertile due to a failure of implantation." (PMID 24204576, 2013). "Mutations in the LIF gene have been described in nulligravid infertile women, and have been hypothesized to cause transcription abnormalities and decreased LIF expression." (PMID 22520363, 2012). "As such, LIF mRNA and protein, both content and localization within the endometrium, have been studied in a variety of infertility cohorts including unexplained infertility, recurrent implantation failure, as well as in diseases associated with infertility such as adenomyosis and endometriosis." (PMID 37033980, 2023). "Failed expression of endometrial LIF may cause infertility in animals." (PMID 35012573, 2022). "However, during the middle and late luteal phase, LIF expression in patients with infertility from unknown causes was significantly lower than that in healthy subjects." (PMID 23226768, 2012). "In addition, in some women with endometriosis associated infertility, IL-11 and LIF immunoreactivity are reduced in glandular epithelium suggesting that both cytokines may also contribute to the pathology of infertility of unknown cause." (PMID 18047677, 2007). "Clinically, fertile women have been found to have higher LIF immunostaining upon biopsies compared to infertile women." (PMID 40733669, 2025). "LIF administration has emerged as an alternative approach to enhance embryo implantation because this factor is dysregulated in infertile women experiencing recurrent implantation failure." (PMID 39151945, 2024). "Studies have reported that leukemia inhibitory factor (LIF) and its JAK2/STAT3 signaling pathway are among the pathways most closely associated with infertility due to abnormal endometrial receptivity." (PMID 38896093, 2024). "In female LIF-KO mice, infertility results from disruption of embryo apposition to the endometrium and a defect in decidualization, hindering normal implantation and pregnancy development." (PMID 39120268, 2024).
Infertility (continued). "While we provide previously unexplored dimensions of LIF in endometriosis pathophysiology beyond infertility, we acknowledge some of the limitations of the work that are inherent to endometriosis research." (PMID 37033980, 2023). "In patients with mild to moderate endometriosis who are experiencing infertility, LIF expression was reduced in endometrial samples obtained during the mid-secretory phase, combined with elevated IL-6 and IL-1α in the peritoneal fluid (PF)." (PMID 37033980, 2023). "The author concluded that the majority of infertile women (especially those with RIF) have a dysregulation of LIF production in the endometrium during both the proliferative and the secretory phases of the cycle." (PMID 38139443, 2023). "The women with infertility under the age of 35 (POSEIDON group 1) were associated with a higher frequency of TG/GG genotypes and G allele of LIF (rs929271)." (PMID 36769444, 2023). "Data obtained from clinical studies showed that the endometrial expression of LIF is significantly higher at the time of implantation in fertile women than in infertile women." (PMID 37266451, 2023). "Our data showed that the women with infertility under the age of 35 (POSEIDON group 1) were associated with a higher frequency of TG/GG genotypes and G allele of LIF (rs929271)." (PMID 36769444, 2023). "This study found decreased levels of HOXA11 and LIF in the endometrium of infertile patients with fibroids compared to the control samples." (PMID 37108180, 2023). "Genetic model analyses in infertile young women revealed that the TG or GG genotype in the LIF resulted in fewer oocytes retrieved and fewer mature oocytes relative to the TT genotypes." (PMID 36769444, 2023). "We found that women with infertility under the age of 35 (POSEIDON group 1 and 3) were associated with a higher frequency of LIF (rs929271) TG/GG genotypes and G allele." (PMID 36769444, 2023). "In endometriosis, LIF has only been investigated for its contributions to infertility however its presence within the lesion microenvironment and impact on lesion maintenance and the immune contexture remained unexplored." (PMID 37033980, 2023). "They found a significantly higher LIF score in the control group compared with the unexplained infertile group across the luminal, glandular and stromal epithelium (p < 0.05)." (PMID 36572790, 2023). "This reduced eutopic LIF expression is in accordance with infertility research, demonstrating that the endometrium of endometriosis patients has aberrant LIF expression during the secretory phase." (PMID 37033980, 2023). "While this highlights the potential involvement of LIF in infertility, LIF is a multifaceted cytokine which plays additional roles in the maintenance of cell stemness and immunomodulation." (PMID 37033980, 2023). "Influence of LIF in human infertility, miscarriage and assisted pregnancy Brief description of the study." (PMID 36329823, 2022). "Surprisingly, recombinant LIF, administered to infertile women subcutaneously for 7 days starting on the day of embryo transfer, significantly reduced clinical pregnancy rates." (PMID 36329823, 2022). "In humans, altered expression of LIF in infertile women with unexplained infertility has been demonstrated." (PMID 35224652, 2022). "In accordance with the animal studies, reduced LIF production is observed in women with unexplained infertility and recurrent miscarriages compared to healthy fertile women in many studies, although there are exceptions." (PMID 36329823, 2022). "The LIF pathway is also disrupted in the endometrium of patients with unexplained infertility, particularly those with endometriosis and endometrioma." (PMID 35012573, 2022). "There was also a significant decrease in both protein and mRNA levels of LIF and gp130 in most women with unexplained infertility and RIF at the proliferative and the secretory phases." (PMID 36704201, 2022).